RN7SL697P (RNA, 7SL, cytoplasmic 697, pseudogene)
Gene: Miscellaneous RNA gene on chromosome X (154,495,815 to 154,496,113, reverse strand). Ensembl gene ENSG00000264484.
Homologues: Orthologues: chimpanzee Metazoa_SRP (100% identical), macaque Metazoa_SRP (96% identical). Paralogues in human: RN7SL1 (81% identical), RN7SL2 (81% identical), RN7SL663P (81% identical), RN7SL3 (80% identical), RN7SL45P (80% identical), RN7SL88P (80% identical), RN7SL597P (79% identical), RN7SL664P (79% identical), RN7SL709P (79% identical), Metazoa_SRP (79% identical), RN7SL126P (79% identical), RN7SL296P (79% identical), and 705 more.